PON1 (paraoxonase 1)
Diseases named in the same sentence as PON1 in open-access papers (continued):
Sharing a sentence is not in itself a finding about the gene and the disease.
COVID-19 (continued). "Proteomic studies have observed increased PON1 protein expression in high-density lipoproteins of COVID-19 patients and suggested that this enzyme can be a marker of recovery." (PMID 35883435, 2022). "PON1 activity was similar in COVID-19-positive patients and in patients with cancer or morbid obesity, when the latter group was considered together or when considered separately according to disease." (PMID 35883435, 2022). "The present study found a marked decrease in PON1 activity and an increase in PON1, CCl2, and galectin-3 concentrations in COVID-19 positive hospitalized patients, compared to healthy individuals." (PMID 34205807, 2021). "We think that the most remarkable result of our study is the sharp reduction in PON1 activity in COVID-19 positive patients, which seems specific to this infectious disease." (PMID 34205807, 2021). "The lower the monocyte concentrations and the PON1 activity, the more likely a patient was to be COVID-19 positive." (PMID 34205807, 2021). "We observed an inverse prediction (SHAP value of −0.6) to be COVID-19 positive at higher PON1 activity and monocyte concentrations." (PMID 34205807, 2021). "Surprisingly, although previous reports have shown that COVID-19 patients were characterized by a lower PON-1 activity and a rise in total PON-1 concentration, we found higher PON-1 activity in COVID-19 patients compared to controls." (PMID 34945250, 2021). "The impact on GSH and PON1 is particularly pronounced, suggesting that these components may be crucial in modulating the severity of COVID-19." (PMID 40723899, 2025). "The current evidence indicates that serum Paraoxonase-1 (PON1) levels, particularly arylesterase activity, are better suited as a diagnostic biomarker for COVID-19 rather than a prognostic biomarker." (PMID 41209585, 2025). "However, given their known ability to increase oxidative stress and alter HDL structure and composition, it is plausible that these infections also lead to changes in PON1 activity similar to those observed in COVID-19, albeit possibly to a lesser extent." (PMID 40723899, 2025). "PON1’s ability to degrade oxidized lipids and specific toxins like organophosphates supports its protective role against systemic OS, particularly during infections such as COVID-19, where oxidative imbalance is a key pathological feature." (PMID 41209585, 2025). "Although reduced PON1 activity has been consistently reported in COVID-19 and associated with disease severity, no pharmacological interventions have been developed to restore PON1 function." (PMID 40723899, 2025). "Whether increasing PON1 activity could mitigate oxidative stress or reduce complications in viral infections such as COVID-19 or influenza remains an open question." (PMID 40723899, 2025). "The results from the present study suggest that the widespread determination of serum PON1 arylesterase activity may be a useful parameter for the community-based diagnosis of COVID-19." (PMID 35883435, 2022). "There are very few data on PON1 alterations in COVID-19 and on the role that this enzyme may play in the course of the disease." (PMID 35883435, 2022). "Our results suggest that the determination of PON1 activity in serum may be a useful marker for the diagnosis of COVID-19." (PMID 34205807, 2021). "Data on the alterations in PON1 levels in COVID-19 is scarce, but recent studies show that it may be important." (PMID 34205807, 2021). "The little data existing seems to suggest two different roles for PON1 in COVID-19, depending on whether it is present in the circulation or within cells." (PMID 34205807, 2021). "SAA levels and PON-1 activity were lower in the control cohort compared to COVID-19 patients." (PMID 34945250, 2021). "We suggest that the measurement of serum PON1 activity may be a useful marker for the diagnosis of COVID-19." (PMID 34205807, 2021).
COVID-19 (continued). "PON1 and KNG1 levels significantly decreased in moderate patients compared to controls and showed a tendency towards a significant decrease in our severe COVID-19 patients compared to healthy controls." (PMID 38791465, 2024). "In acute COVID-19, changes in the HDL proteome have been described as decreased antioxidative capacity, namely less apolipoprotein A-I and paraoxonase 1, and increased acute phase protein and serum amyloid A." (PMID 38674105, 2024). "Among these connections, ADHD exerts a promotion effect on COVID-19 through the inhibition of OXT and PON1 and the promotion of CRP, AR, and TNF." (PMID 38066446, 2023). "Literature-based data mining and construction of the molecular pathways revealed a total of seven genes connecting ADHD with COVID-19, including CRP, PON1, AR, OXT, IL6, TNFSF12, and IL10.." (PMID 38066446, 2023). "We aimed to investigate the alterations in the circulating levels of PON1, CCL2, and galectin-3 in 126 patients with COVID-19 and their interactions with clinical variables and analytical parameters." (PMID 34205807, 2021). "Of the significantly dysregulated proteins, selected immune-related proteins PZP, SELENOP, PON1, and CBP2 were validated as candidate prognostic biomarkers for COVID-19 symptomatology." (PMID 34566994, 2021). "Pathway analysis identified several immunity-related genes that may link ADHD to COVID-19, including CRP, OXT, IL6, PON1, AR, TNFSF12, and IL10." (PMID 38066446, 2023). "PON1 activity was the parameter with the greatest power to discriminate between patients who were either positive or negative for COVID-19, while their levels of CCL2 and galectin-3 were similar." (PMID 34205807, 2021). "Regarding COVID-19, PON1 has been shown to increase in protein levels from nonsevere to severe patients and we found the protein underrepresented in nonsevere and recovered patients, thus suggesting a biomarker for disease recovery." (PMID 34566994, 2021). "A proteomic study found decreased PON1 expression in the HDL of COVID-19 patients; the role of PON1 in COVID-19 may be different depending on whether the enzyme is present in the circulation or within the cells." (PMID 34356595, 2021). "We found significant direct correlations between galectin-3, CCL2, PON1, IL-6, IL-10, CRP, ACE2, and angiotensin II concentrations in COVID-19 positive patients as well as with aminotransferase activities and triglycerides, and inverse correlations with HDL-cholesterol." (PMID 34205807, 2021). "Considering only the COVID-19 positive patients, we found that those with higher concentrations of IL-10 (>200 ng/L) or IL-6 (>100 ng/L) had higher concentrations of CCL2, galectin-3, and PON1 concentrations." (PMID 34205807, 2021). "The present study hypothesizes that SARS-CoV-2 infection can produce alterations in the expression of PON1, CCL2, and galectin-3, which may be involved in the pathophysiology of COVID-19." (PMID 34205807, 2021). "As such, elevated levels of PON1 indicate the absence of COVID-19, but low levels may be present in various other chronic diseases." (PMID 35883435, 2022). "The degree of COVID-19 severity did not influence PON1 levels." (PMID 35883435, 2022). "In particularwe observed a decrease in the HDL components APOA4 and APOC1 in both COVID-19 non-ICU and ICU/F patients (cluster 3) while APOA2, APOD, APOH, APOM and the HDL-associated PON1 protein appear to be decreased mainly in COVID-19 non-ICU patients (cluster 7)." (PMID 36348270, 2022). "Moreover, the arylesterase (AE) activity of PON1 and the anti-oxidative (AO)-capacity of apoB-depleted serum were also lower in COVID-19 patients (p = 0.034, p < 0.001) when compared to non-COVID-19 pneumonia patients." (PMID 36290581, 2022). "PON1 activity in the serum of COVID-19 patients may be lower for several, though not mutually exclusive, reasons." (PMID 34205807, 2021).
COVID-19 (continued). "Indeed, when PON1 activity was higher than 100 U/L, and monocyte concentrations were higher than 2 × 109/L, the model predicted an absence of COVID-19." (PMID 34205807, 2021). "COVID-19 positive patients had lower PON1 activities and galectin-3 concentrations, and higher PON1, CRP, IL-10, and ACE2 concentrations than COVID-19 negative patients." (PMID 34205807, 2021). "Considering the objectives of our study, we highlight that there were significant, direct correlations between CCl2, galectin-3, PON1 concentration, CRP, IL-10, IL-6, and angiotensin II in COVID-19 positive patients, but not in the COVID negative ones." (PMID 34205807, 2021). "We found that patients with COVID-19 had significantly lower serum activities of LCAT and markedly impaired HDL functionality, such as reduced cholesterol efflux capacity, AE-activity of PON1, and AO-capacity, when compared to non-COVID pneumonia patients." (PMID 36290581, 2022).
Hypercholesterolemia (23 papers, 2009 to 2025). An increased concentration of cholesterol in the blood. "A study involving patients with type IIb hypercholesterolaemia found that there was a significant increase in the PON-1 paraoxoanse activity after three months of statin treatments and increased PON activity associated with lower levels of triglycerides." (PMID 31311140, 2019). "A study with anthocyanin supplementation in subjects with hypercholesterolemia demonstrated an increased in HDL-associated PON1 activity and an improvement in cholesterol efflux capacity." (PMID 30544803, 2018). "This study aimed at exploring the implications of PON1 polymorphism in the individuals affected by familial hypercholesterolemia (FH)." (PMID 30044465, 2018). "In conclusion, from the results obtained by the present study, Se supplementation appears to be protective in experimental hypercholesterolemia by restoring the anti-oxidative properties of the HDL associated enzyme PON1." (PMID 20015371, 2009). "Whereas, the data is not contradictory compared to interventions with VOO enriched with polyphenols (FVOO and FVOOT) in hypercholesterolemia, because PON1 activity and CEC were improved after FVOOT intervention and VOO, FVOO and FVOOT, respectively." (PMID 33809504, 2021). "As hypercholesterolemia impacts PON1 activity in mice, we next examined the PON1 levels and activity in FH patients versus control subjects." (PMID 32629758, 2020). "Antioxidant properties of statins demonstrated on animals were also verified in human studies, where individuals with hypercholesterolemia presented significant reduction in oxidative stress markers and increased PON1 activity after statin therapy." (PMID 27213056, 2016). "The present study was aimed to study HDL associated enzymes i.e. PON1 and PAF-AH under experimental hypercholesterolemia and their possible modulation on selenium (Se; an antioxidant) supplementation." (PMID 20015371, 2009). "In conclusion, Se supplementation appears to be protective in experimental hypercholesterolemia by restoring the antioxidant properties of the HDL associated enzyme, PON1." (PMID 20015371, 2009). "Consistent with this axis, human cohort data in untreated familial hypercholesterolemia demonstrate network correlations among PON1 arylesterase activity, MMP-9, and inflammatory mediators (sCD40L, S1P), positioning PON1 within an HDL-inflammation-protease module relevant to endothelial dysfunction." (PMID 41304763, 2025). "In addition to controlling high levels of cholesterol, there is a need to regularly monitor PON1 status of hypercholesterolemia patients and normal family members." (PMID 30044465, 2018). "In summary, previous studies and the results presented here suggest that the hepatoprotective role of açai in the development of NAFLD is partly mediated by PON1, an antioxidant enzyme also involved in diseases such as hypercholesterolemia, atherogenesis, and neurological disorders." (PMID 27642496, 2016). "PON1 not only affects the process of cholesterol efflux via an ABCA1 dependent pathway, but also shows an antioxidative role in familial hypercholesterolemia; so its activity is an adjunctive index of altered lipoprotein metabolism." (PMID 24971380, 2014). "Importantly, HDL from subjects with familial hypercholesterolemia (FH-HDL) versus controls had increased MDA-apoAI adducts, and PON1 activity was also impaired in FH." (PMID 32629758, 2020). "PON1 genotype and activity are not being monitored in routine clinical practice for the management of hypercholesterolemia." (PMID 30044465, 2018).
Hypercholesterolemia (continued). "The aim of the study was to assess the effect of 5α,6α-epoxycholesterol on experimentally induced hypercholesterolemia in rabbits, and the levels of homocysteine (HCY), asymmetric dimethylarginine (ADMA), paraoxonase-1 (PON-1), and inflammatory parameters (IL-6, TNF-α, CRP)." (PMID 29713239, 2018). "Despite having hypertriglyceridemia and hypercholesterolemia, patients may also have potent PON1 activity and this finding shows that the HDL cholesterol level is not correlated with PON activity." (PMID 25241610, 2014).
rheumatoid arthritis (23 papers, 2007 to 2026). A chronic, systemic autoimmune disorder characterized by inflammation in the synovial membranes and articular surfaces. "This research aims to reveal the mechanisms of the effect of the Paraoxonase 1 (PON1) gene on response to leflunomide (LEF) in rheumatoid arthritis (RA) patients, in terms of single nucleotide polymorphism (SNP), DNA methylation levels." (PMID 40183079, 2025). "In rheumatoid arthritis (RA), an association has been demonstrated between the manifestation of the condition and a deficiency of PON1." (PMID 40227251, 2025). "Because oxidized lipid mediators have also been implicated in the pathogenesis of rheumatoid arthritis (RA), we evaluated the role of PON1 in murine inflammatory arthritis." (PMID 33033318, 2020). "Downregulation of OIP5‐AS1, the resulting increase in miR‐448 and correlated decrease in PON1 in synovial tissues, contributes to the inflammatory symptoms of rheumatoid arthritis." (PMID 35040588, 2022). "OIP5‐AS1's mechanism of action in rheumatoid arthritis is based on interactions with miR‐448, whereby it indirectly impacts levels of paraoxonase 1 (PON1), a miR‐448 target mRNA." (PMID 35040588, 2022). "The antioxidant effect of PON1 has been confirmed in a series of diseases, such as cardiovascular disease, chronic liver disease, metabolic disease, rheumatoid arthritis, endometriosis, and childhood autism." (PMID 33628379, 2021). "In a double-blind randomized controlled trial carried out in 90 female patients with rheumatoid arthritis receiving 1 g of fish oil or a placebo in addition to conventional treatment, fish oil supplementation significantly increased PON1 activity." (PMID 28212288, 2017). "A higher dose (10 mL/day) pomegranate extract for 12 weeks was found to increase PON1 in patients with active rheumatoid arthritis." (PMID 28212288, 2017). "The patients with rheumatoid arthritis showed a significantly lower serum PON1 (paraoxon) activity (mean 131 μmol/min/L) than that of healthy control subjects (164 μmol/min/L)." (PMID 24228251, 2013). "The ratio of PON1 to SAA was lower in patients with rheumatoid arthritis than in healthy control subjects." (PMID 24228251, 2013). "Moreover, a TNF-alpha antagonist therapy in rheumatoid arthritis patients led to enhanced PON1 levels concurrent with elevated anti-oxidative capacities of HDLs and lowered inflammatory status." (PMID 21569287, 2011). "In addition, the activity of PON1 has been reported to be significantly reduced in some conditions accompanying oxidative stress and inflammatory conditions, including rheumatoid arthritis, ulcerative colitis and Behcet's disease." (PMID 17362500, 2007). "As a result, PON1 is considered a protective enzyme for several oxidative-stress-related diseases, including cancer, diabetes, infertility, coronary artery disease, and rheumatoid arthritis (RA)." (PMID 38138163, 2023). "Therefore, PON-1 Q192R polymorphism might not be associated with the incidence of rheumatoid arthritis among Saudi population." (PMID 25406539, 2014). "In numerous pathological conditions like rheumatoid arthritis, impaired PON-1 activity and reduced HDL quantity and particle size were noted." (PMID 38790634, 2024). "Although the relationship between PON-1 192 activity and polymorphism in rheumatoid arthritis was investigated, the correlation between the serum levels of RF and anti-CCP-2 Ab and PON-1 192 activity and polymorphism is not cleared." (PMID 25406539, 2014).